AKT1 (AKT serine/threonine kinase 1)
Description:
AKT1 is one of 3 closely related serine/threonine-protein kinases (AKT1, AKT2 and AKT3) called the AKT kinase, and which regulate many processes including metabolism, proliferation, cell survival, growth and angiogenesis. This is mediated through serine and/or threonine phosphorylation of a range of downstream substrates. Over 100 substrate candidates have been reported so far, but for most of them, no isoform specificity has been reported. AKT is responsible of the regulation of glucose uptake by mediating insulin-induced translocation of the SLC2A4/GLUT4 glucose transporter to the cell surface (By similarity). Phosphorylation of PTPN1 at 'Ser-50' negatively modulates its phosphatase activity preventing dephosphorylation of the insulin receptor and the attenuation of insulin signaling (By similarity). Phosphorylation of TBC1D4 triggers the binding of this effector to inhibitory 14-3-3 proteins, which is required for insulin-stimulated glucose transport. AKT also regulates the storage of glucose in the form of glycogen by phosphorylating GSK3A at 'Ser-21' and GSK3B at 'Ser-9', resulting in inhibition of its kinase activity (By similarity). Phosphorylation of GSK3 isoforms by AKT is also thought to be one mechanism by which cell proliferation is driven (By similarity). AKT also regulates cell survival via the phosphorylation of MAP3K5 (apoptosis signal-related kinase). Phosphorylation of 'Ser-83' decreases MAP3K5 kinase activity stimulated by oxidative stress and thereby prevents apoptosis. AKT mediates insulin-stimulated protein synthesis by phosphorylating TSC2 at 'Ser-939' and 'Thr-1462', thereby activating the mTORC1 signaling pathway, and leading to both phosphorylation of 4E-BP1 and in activation of RPS6KB1. Also regulates the mTORC1 signaling pathway by catalyzing phosphorylation of CASTOR1 and DEPDC5. AKT plays a role as key modulator of the AKT-mTOR signaling pathway controlling the tempo of the process of newborn neurons integration during adult neurogenesis, including correct neuron positioning, dendritic development and synapse formation (By similarity). Part of a positive feedback loop of mTORC2 signaling by mediating phosphorylation of MAPKAP1/SIN1, promoting mTORC2 activation (By similarity). AKT is involved in the phosphorylation of members of the FOXO factors (Forkhead family of transcription factors), leading to binding of 14-3-3 proteins and cytoplasmic localization. In particular, FOXO1 is phosphorylated at 'Thr-24', 'Ser-256' and 'Ser-319'. FOXO3 and FOXO4 are phosphorylated on equivalent sites. AKT has an important role in the regulation of NF-kappa-B-dependent gene transcription and positively regulates the activity of CREB1 (cyclic AMP (cAMP)-response element binding protein). The phosphorylation of CREB1 induces the binding of accessory proteins that are necessary for the transcription of pro-survival genes such as BCL2 and MCL1. AKT phosphorylates 'Ser-454' on ATP citrate lyase (ACLY), thereby potentially regulating ACLY activity and fatty acid synthesis (By similarity). Activates the 3B isoform of cyclic nucleotide phosphodiesterase (PDE3B) via phosphorylation of 'Ser-273', resulting in reduced cyclic AMP levels and inhibition of lipolysis (By similarity). Phosphorylates PIKFYVE on 'Ser-318', which results in increased PI(3)P-5 activity (By similarity). The Rho GTPase-activating protein DLC1 is another substrate and its phosphorylation is implicated in the regulation cell proliferation and cell growth (By similarity). Signals downstream of phosphatidylinositol 3-kinase (PI(3)K) to mediate the effects of various growth factors such as platelet-derived growth factor (PDGF), epidermal growth factor (EGF), insulin and insulin-like growth factor 1 (IGF1). AKT mediates the antiapoptotic effects of IGF1 (By similarity). Essential for the SPATA13-mediated regulation of cell migration and adhesion assembly and disassembly. May be involved in the regulation of the placental development (By similarity). Phosphorylates STK4/MST1 at 'Thr-120' and 'Thr-387' leading to inhibition of its: kinase activity, nuclear translocation, autophosphorylation and ability to phosphorylate FOXO3. Phosphorylates STK3/MST2 at 'Thr-117' and 'Thr-384' leading to inhibition of its: cleavage, kinase activity, autophosphorylation at Thr-180, binding to RASSF1 and nuclear translocation. Phosphorylates SRPK2 and enhances its kinase activity towards SRSF2 and ACIN1 and promotes its nuclear translocation. Phosphorylates RAF1 at 'Ser-259' and negatively regulates its activity. Phosphorylation of BAD stimulates its pro-apoptotic activity. Phosphorylates palladin (PALLD), modulating cytoskeletal organization and cell motility. Phosphorylates prohibitin (PHB), playing an important role in cell metabolism and proliferation. Phosphorylates CDKN1A, for which phosphorylation at 'Thr-145' induces its release from CDK2 and cytoplasmic relocalization. These recent findings indicate that the AKT1 isoform has a more specific role in cell motility and proliferation. Phosphorylates CLK2 thereby controlling cell survival to ionizing radiation. Phosphorylates PCK1 at 'Ser-90', reducing the binding affinity of PCK1 to oxaloacetate and changing PCK1 into an atypical protein kinase activity using GTP as donor. Also acts as an activator of TMEM175 potassium channel activity in response to growth factors: forms the lysoK(GF) complex together with TMEM175 and acts by promoting TMEM175 channel activation, independently of its protein kinase activity. Acts as a regulator of mitochondrial calcium uptake by mediating phosphorylation of MICU1 in the mitochondrial intermembrane space, impairing MICU1 maturation. Acts as an inhibitor of tRNA methylation by mediating phosphorylation of the N-terminus of METTL1, thereby inhibiting METTL1 methyltransferase activity. In response to LPAR1 receptor pathway activation, phosphorylates Rabin8/RAB3IP which alters its activity and phosphorylates WDR44 which induces WDR44 binding to Rab11, thereby switching Rab11 vesicular function from preciliary trafficking to endocytic recycling.
Synonyms: PKB; RAC; PRKBA; AKT; RAC-alpha; PKB-ALPHA
Tractability: Small molecule: a drug acting on it is in phase 2 or 3 trials; a structure with a bound ligand is known; a high-quality ligand is known; it has a high-quality binding pocket; it belongs to a druggable protein family. Antibody: UniProt places it where antibodies can reach, with high confidence; its Gene Ontology location is reachable by antibodies, with high confidence. PROTAC: it is named in the literature on targeted protein degradation; UniProt records ubiquitination sites on it; ubiquitination databases record sites on it; its protein half-life has been measured; a small molecule that binds it is known.
Target class: AGC protein kinase AKT family; Enzyme; Protein Kinase; AGC protein kinase group; Kinase
Chemical probes: A-443654, Akt inhibitor VIII, BAY1125976 (high quality), Borussertib (high quality), INY-03-041 (high quality), PD080885, PD081225, PD081392, PD081418, PD081554, PD081619, PD081825, PD082157, PD082618, PD083125, PD083944, PD084502, PD084778, PD084884, capivasertib (high quality)
Safety:
Unwanted effects reported when the protein is acted on. In parentheses: how it was acted on, where the effect was seen, and who reports it.
apoptototic cell death in cancer cells (inhibition; cardiovascular system; source: Urban et al. (2012))
hyperglycemia (inhibition; cardiovascular system; source: Urban et al. (2012))
heart disease (cardiovascular system; source: Force et al. (2011))
Gene: Protein-coding gene on chromosome 14 (104,769,348 to 104,799,934, reverse strand). Ensembl gene ENSG00000142208.
Subcellular location: Cytoplasm; Nucleus; Cell membrane; Mitochondrion intermembrane space
Subcellular location (Human Protein Atlas): End piece; Microtubules; Nucleoplasm; Principal piece; Basal body; Calyx; Perinuclear theca; Primary cilium
Pathways (Reactome):
Signal Transduction: AKT phosphorylates targets in the cytosol; AKT phosphorylates targets in the nucleus; Deactivation of the beta-catenin transactivating complex; Downregulation of ERBB2:ERBB3 signaling; Estrogen-dependent nuclear events downstream of ESR-membrane signaling; Extra-nuclear estrogen signaling; G beta:gamma signalling through PI3Kgamma; Inhibition of TSC complex formation by AKT (PKB); Integrin signaling; MTOR signalling; Negative regulation of NOTCH4 signaling; Negative regulation of the PI3K/AKT network; PI5P, PP2A and IER3 Regulate PI3K/AKT Signaling; PIP3 activates AKT signaling; PTK6 Regulates RTKs and Their Effectors AKT1 and DOK1; Regulation of PTEN stability and activity; VEGFR2 mediated vascular permeability
Gene expression (Transcription): RUNX2 regulates genes involved in cell migration; Regulation of localization of FOXO transcription factors
Cellular responses to stimuli: High laminar flow shear stress activates signaling by PIEZO1 and PECAM1:CDH5:KDR in endothelial cells; KEAP1-NFE2L2 pathway; Mechanical load activates signaling by PIEZO1 and integrins in osteocytes; Mitochondrial unfolded protein response (UPRmt)
Immune System: CD28 dependent PI3K/Akt signaling; Co-inhibition by CTLA4; FLT3 Signaling; Interleukin-4 and Interleukin-13 signaling
Cell Cycle: Cyclin A:Cdk2-associated events at S phase entry; Cyclin E associated events during G1/S transition
Disease: Constitutive Signaling by AKT1 E17K in Cancer; SARS-CoV-2 targets host intracellular signalling and regulatory pathways
Metabolism: Tetrahydrobiopterin (BH4) synthesis, recycling, salvage and regulation; eNOS activation
Metabolism of RNA: Butyrate Response Factor 1 (BRF1) binds and destabilizes mRNA; KSRP (KHSRP) binds and destabilizes mRNA
Vesicle-mediated transport: RAB GEFs exchange GTP for GDP on RABs
and 3 more pathways
Gene Ontology:
Molecular function: 14-3-3 protein binding; ATP binding; calmodulin binding; identical protein binding; kinase activity; kinase binding; nitric-oxide synthase regulator activity; phosphatidylinositol-3,4,5-trisphosphate binding; phosphatidylinositol-3,4-bisphosphate binding; potassium channel activator activity; protein binding; protein homodimerization activity; protein kinase activity; protein serine kinase activity; protein serine/threonine kinase activity; protein serine/threonine/tyrosine kinase activity; TORC2 complex binding; enzyme binding; protein serine/threonine kinase inhibitor activity; protein kinase binding
Biological process: activation-induced cell death of T cells; cell migration involved in sprouting angiogenesis; cellular response to epidermal growth factor stimulus; cellular response to insulin stimulus; cellular response to nerve growth factor stimulus; cellular response to oxidised low-density lipoprotein particle stimulus; complement receptor mediated signaling pathway; epidermal growth factor receptor signaling pathway; insulin receptor signaling pathway; insulin-like growth factor receptor signaling pathway; interleukin-18-mediated signaling pathway; intracellular signal transduction; maintenance of protein location in mitochondrion; negative regulation of apoptotic process; negative regulation of autophagy; negative regulation of cGAS/STING signaling pathway; negative regulation of cilium assembly; negative regulation of fatty acid beta-oxidation; negative regulation of hydrogen peroxide-induced neuron intrinsic apoptotic signaling pathway; negative regulation of leukocyte cell-cell adhesion; negative regulation of long-chain fatty acid import across plasma membrane; negative regulation of lymphocyte migration; negative regulation of protein localization to lysosome; negative regulation of protein ubiquitination; negative regulation of proteolysis; and 79 more
Cellular component: cytoplasm; cytosol; membrane; nucleoplasm; nucleus; plasma membrane; protein-containing complex; vesicle; cell cortex; lamellipodium; mitochondrial intermembrane space; cell-cell junction; ciliary basal body; glutamatergic synapse; mitochondrion; postsynapse; spindle
Genetic constraint (gnomAD): Loss-of-function variants: 21 observed, 63.81 expected, observed/expected ratio (o/e) 0.33, 90% interval 0.23 to 0.47. The upper end of that interval is the gene's LOEUF score, 0.47, which puts it in group 2 of 6, group 1 being the genes least tolerant of losing a copy. Missense variants: 382 observed, 684.64 expected, observed/expected ratio (o/e) 0.56, 90% interval 0.51 to 0.61. Synonymous variants: 257 observed, 260.15 expected, observed/expected ratio (o/e) 0.99, 90% interval 0.89 to 1.1.
Gene-disease validity (ClinGen):
ClinGen rates the evidence that AKT1 causes each of these diseases.
Cowden syndrome 6 (autosomal dominant): Limited.
Cancer hallmarks: change of cellular energetics (promotes); proliferative signalling (promotes); escaping programmed cell death (promotes); angiogenesis (promotes); invasion and metastasis (promotes); invasion and metastasis (suppresses); angiogenesis (promotes or suppresses); genome instability and mutations (suppresses); suppression of growth (promotes)
Homologues: Orthologues: chimpanzee AKT1 (100% identical), macaque AKT1 (99% identical), mouse Akt1 (98% identical), guinea pig AKT1 (98% identical), tropical clawed frog akt1 (93% identical), pig AKT1 (90% identical), dog AKT1 (90% identical), rat Akt1 (83% identical), zebrafish akt1 (46% identical). Paralogues in human: AKT3 (83% identical), AKT2 (81% identical), PRKCQ (41% identical), PRKCD (39% identical), PDPK1 (29% identical).
Diseases named in the same sentence as AKT1 in open-access papers:
AKT1 is named in the same sentence as 948 diseases in open-access papers, as found by Europe PMC text mining. Sharing a sentence is not in itself a finding about the gene and the disease. The quoted sentences say what the papers report.
breast cancer (1,775 papers, 2002 to 2026). A primary or metastatic malignant neoplasm involving the breast. "AKT1 is a well-established oncogenic factor implicated in the development of multiple malignancies, including lung cancer, nasopharyngeal carcinoma, breast cancer, hepatocellular carcinoma, and ovarian cancer." (PMID 41584043, 2026). "For example, AKT1 PH domain somatic mutations are found in 8.2% of breast cancers, 2% of ovarian cancers, and 5.9% of colorectal cancers." (PMID 40746599, 2025). "In particular, Akt‐1 is associated with a common mutation in breast cancer known as E17K (AKT1 mutations)." (PMID 39648951, 2025). "It was observed that oncogenic mutation in PI3K is directly associated with either activating subsequent mutations in PIK3CA or Akt1 or is linked with decreased expression of PTEN thereby further complicating breast cancer." (PMID 40176859, 2025). "As such, targeted therapies play an important role, particularly in the PIK3/AKT pathway, with PIK3CA mutations prevalent in HR+ breast cancer (34.5%) and AKT1 and PTEN mutations restricted to this subgroup." (PMID 40243903, 2025). "Capivasertib (novel inhibitor): Approved in combination with fulvestrant for patients with HR-positive, HER2-negative breast cancer with a PIK3CA/AKT1/PTEN mutation." (PMID 41157256, 2025). "Given the relatively low prevalence of AKT1 mutations in breast cancer, the majority of specimens are AKT1WT tumors." (PMID 40135844, 2025). "Somatic mutations in AKT1 have been identified in various human cancers, including breast cancer, colorectal cancer, and ovarian cancer." (PMID 40896440, 2025). "Aberrant activation of AKT1 has been associated with cancer progression, metastasis, and resistance to therapy, particularly in breast cancer." (PMID 39275052, 2024). "The interplay between PPARG and AKT1 is also evident in the context of cancer, with studies identifying their association in colorectal cancer, acute myeloid leukemia, and breast cancer." (PMID 38505269, 2024). "AKT1 (E17K) mutation was reported in breast cancer, meningioma, colorectal cancer, lung cancer, bladder, and ovarian cancer in different frequencies." (PMID 39329938, 2024). "Clinical studies evaluating the efficacy of AKT inhibitors in breast cancer patients with AKT1 mutations underscore the role of AKT1 as a predictive biomarker." (PMID 38172946, 2024). "The AKT1 E17K mutation is notably frequent in breast cancer, while AKT2 amplification or overexpression is common in breast, ovarian, and prostate cancers." (PMID 39596452, 2024). "If successful, these inhibitors hold promise as a treatment option for certain breast cancer patients with AKT1-mutated tumors." (PMID 38172946, 2024). "Mutations in PTEN and PIK3R1 have been described in different histological types of canine mammary tumors (both benign and malignant), while AKT1 mutations were exclusively observed in complex carcinomas, suggesting that they are tissue-specific." (PMID 37835752, 2023). "The mutations in the AKT1 gene have been associated with different types of cancer, such as lung, colorectal, ovarian, and breast cancer." (PMID 37511907, 2023). "Capivasertib has shown promising efficacy in breast cancer and has significant activity against AKT1-E17K-mutated cancers." (PMID 37489050, 2023). "The most common AKT1 gene variants identified by whole exome sequencing in all our breast cancer cases were AKT-1 rs1130233 C > T, c.726G > A, p.Glu242, and p.E242." (PMID 36831624, 2023). "Our findings indicated a strong association between the AKT1 rs1130233-GA genotype with the breast cancer susceptibility in the codominant model, with an OR = 3.20, (95%) CI = 1.6829–6.084, RR = 1.84, and p < 0.0004." (PMID 36831624, 2023). "PH and SEC7 domain-containing protein 3 variant PSD3:18 found downregulated in the AKT1 silenced sample compared to control was reported downregulated in breast cancer." (PMID 35892586, 2022).